CRP (C-reactive protein)
Diseases named in the same sentence as CRP in open-access papers (continued):
Sharing a sentence is not in itself a finding about the gene and the disease.
leukocytosis (1,537 papers, 2006 to 2026). "Our results were in agreement with previous reports that showed leukocytosis and high levels of CRP in association with disease morbidity and mortality." (PMID 40017474, 2025). "Studies have shown that leukocytosis, lymphopenia, anemia, and elevated CRP and ESR levels were risk factors for increased cardiac involvement." (PMID 41226731, 2025). "Fever, hypothermia, fast breath, tachycardia, chest retraction, leukopenia or leukocytosis, cyanosis, hypoxia, and an elevated C-reactive protein are all crucial diagnostic indicators." (PMID 41311440, 2025). "Laboratory tests, including leukocytosis, neutrophilia, and elevated C-reactive protein (CRP), improve diagnostic yield, but their specificity remains limited." (PMID 41141184, 2025). "Imaging revealed extensive pulmonary consolidation, and laboratory findings showed marked leukocytosis dominated by neutrophils with significantly elevated CRP levels, features typically associated with severe bacterial infection." (PMID 41341106, 2025). "At 20 days postpartum, cervical cultures confirmed Escherichia coli colonization, with associated leukocytosis and elevated C-reactive protein (CRP) levels (58 mg/L with a 5 mg/L normal limit)." (PMID 40352001, 2025). "Intrauterine inflammation is associated with leukocytosis and elevated maternal and neonatal CRP values." (PMID 40310124, 2025). "The combination of placental histopathology (chorioamnionitis/funisitis) and maternal inflammatory markers (leukocytosis, CRP) further enhances risk assessment." (PMID 41010644, 2025). "Chronic inflammation is associated with blood leukocytosis, increased serum levels of C-reactive protein, fibrinogen and inflammatory cytokines." (PMID 40507423, 2025). "While clinical examination and established biomarkers like leukocytosis and CRP form the diagnostic cornerstone, their limitations in atypical presentations necessitate the exploration of supplementary indicators." (PMID 41185821, 2025). "Laboratory findings, such as leukocytosis and elevated CRP levels, occur in both conditions; however, appendiceal diverticulitis is more commonly associated with leukocytosis (>15 × 109/L) and significantly higher CRP levels." (PMID 40136596, 2025). "Additional diagnostic tests revealed leukocytosis (20,520 cells/μL), CRP 99.5 mg/L, amniotic membrane culture positive for L. monocytogenes, and placental signs of chorioamnionitis consistent with listeria infection." (PMID 39597695, 2024). "Severe cases were also significantly associated with anemia, leukocytosis, neutrophilia, lymphopenia, decreased platelet count, increased CRP, D-dimer, ALT, and creatinine (p < 0.001)." (PMID 38263160, 2024). "Although they are not totally the same, hypoglycemia has been reported to be associated with increased C-reactive protein and proinflammatory cytokines, reactive oxygen species and leukocytosis." (PMID 38773666, 2024). "Blood tests revealed leukocytosis, markedly elevated C-reactive protein, and a newly developed iron deficiency anemia." (PMID 38363399, 2024). "In our cohort, laboratory markers of inflammation were associated with higher stages of AKI, such as leukocytosis and elevated CRP levels." (PMID 39597864, 2024). "Subsequent diagnostic procedures revealed leukocytosis (14,300 cells/μL), elevated CRP (52 mg/L), placental culture positive for L. monocytogenes, and placental signs of chorioamnionitis consistent with listeria infection." (PMID 39597695, 2024). "Additional diagnostic procedures revealed leukocytosis (25,610 cells/μL), elevated CRP levels (106 mg/L), and positive results for L. monocytogenes in both blood and placental cultures." (PMID 39597695, 2024). "AmygA associated with heightened bone marrow activity, leukocytosis, and C-reactive protein (P<0.05 each)." (PMID 37540647, 2023). "The male gender, an age < 1 month, leukocytosis > 15 × 109/L, or a CRP > 2 mg/dL increased the risk of SBIs." (PMID 37510751, 2023).
leukocytosis (continued). "This disease is associated with leukocytosis with lymphopenia, neutrophilia, and elevated levels of d-dimer, and C-reactive protein, ferritin, procalcitonin, and lactate dehydrogenase." (PMID 37363332, 2023). "A prospective study from Turkey reported that leukocytosis and elevated CRP were associated with SAP." (PMID 37954725, 2023). "Older age, interstitial lung disease, presence of cavity, consolidative radiologic feature, anemia, high CRP, and leukocytosis were significantly associated with increased radiographic progression after adjusting for covariates." (PMID 37147519, 2023). "Multivariate logistic regression has shown leukocytosis and intensive care unit admission as risk factors for bacterial infections and C-reactive protein, together with the length of hospital stay, as mortality predictors." (PMID 36671345, 2023). "We found that the male gender, an age < 1 month, leukocytosis, and an elevated CRP increased the risk of SBIs; however, in infants with these markers, the presence of respiratory symptoms decreased the risk of SBIs." (PMID 37510751, 2023). "After adjusting for covariates, older age, interstitial lung disease, presence of cavity, consolidative radiologic feature, anemia, high CRP, and leukocytosis were significantly associated with increased radiographic progression." (PMID 37147519, 2023). "In multivariate analysis, CRP > 100 mg/l and leukocytosis at admission were significantly associated with death, MV and ICU treatment." (PMID 36016322, 2022). "In a subgroup, combined leukocytosis and elevated CRP had the strongest association with poor outcome (ORadjusted 2.26[1.76–2.91]) and mortality (ORadjusted 2.43[1.86–3.16]) when compared to combined normal WBC and CRP." (PMID 35622132, 2022). "Low saturation of oxygen values on admission, changes in C-reactive protein, leukocytosis, hyperglycemia, and procalcitonin level were associated with an increased risk of death during hospitalization." (PMID 36231836, 2022). "In a subgroup, we analyzed the association of combined leukocytosis and elevated C-reactive protein (CRP > 10 mg/l) on outcomes." (PMID 35622132, 2022). "We also included a subgroup analysis with combined leukocytosis and elevated CRP which is a novelty and underlined the effect of systemic inflammation on clinical outcomes." (PMID 35622132, 2022). "Elevated inflammatory markers such as CRP and procalcitonin, together with leukocytosis and increased neutrophil count, were associated with higher antibiotic prescriptions." (PMID 35016728, 2022). "Most patients were misdiagnosed as retropharyngeal abscess because retropharyngeal abscess also mainly affects children, causing fever, cervical lymphadenopathy, leukocytosis, and elevated serum C-reactive protein (CRP)." (PMID 36514104, 2022). "Previous studies revealed an association between leukocytosis as well as elevated CRP on admission and more severe strokes and larger infarct volumes." (PMID 35622132, 2022). "The study demonstrated that besides smoking, peripheral leukocytosis and elevated CRP were the most important risk factors for emphysema in PLWH on cART." (PMID 33936110, 2021). "The results also indicate an adverse effect of elevated leukocytosis on the first day of stroke, and of elevated CRP, on the risk of ICB and the functional status of patients on the first days following onset." (PMID 34768603, 2021). "Previous studies of adenovirus pneumonia suggested that male sex, young age, leukocytosis, and elevated C-reactive protein (CRP) levels were associated with severe pneumonia." (PMID 33632148, 2021). "Biologically, IVIg unresponsiveness was associated with inflammation (high CRP and procalcitonin levels, leukocytosis, low albumin level and high lymphocyte count) and hepatic involvement (high AST, ALT and gamma-glutamyl transpeptidase [GGT] levels)." (PMID 32080307, 2020).
leukocytosis (continued). "The results of the present study also indicate that, in the subgroup of patients infected with ribotype 027, higher case fatality ratio was associated with leukocytosis, renal failure and higher CRP." (PMID 32477428, 2020). "High levels of cfDNA were associated with high C-reactive protein, leukocytosis as well as granulocytosis in the recipient." (PMID 32443763, 2020). "While elevated serum levels of CRP probably reflect the activation of systemic inflammation elicited by the surgical injury, leukocytosis in the patients with grade B POPFs is usually associated with a mild infection." (PMID 31582902, 2019). "Elevated levels of C-reactive protein (CRP) and presence of leukocytosis in blood (WBC) were both significantly associated with pediatrician antibiotic prescribing for enterovirus infection (p<0.001)." (PMID 30192893, 2018). "Typical laboratory findings in acute PUUV-caused HFRS are leukocytosis, thrombocytopenia, increased C-reactive protein (CRP) level, and as signs of acute kidney injury (AKI), proteinuria, haematuria and elevated serum creatinine concentration." (PMID 30283445, 2018). "CeDNA strongly correlated with C-reactive protein and leukocytosis, suggesting an association of ceDNA with inflammation in VTE patients." (PMID 29474368, 2018). "Leukocytosis (OR 2.19, 95%CI 1.35–3.55), Thrombocytosis (OR 1.93, 95%CI 1.06–3.51) and CRP (OR 2.91, 95%CI 1.76–4.80) were associated with a solid cancer diagnosis." (PMID 29197366, 2017). "An excess amount of aberrant production causes an inflammatory response such as fever and positive CRP, a kind of leukemoid reaction (leukocytosis >50,000 leukocytes/μL), and paraneoplastic syndrome in clinical oncology." (PMID 27737660, 2016). "DEP caused leukocytosis and a significant increase in plasma C-reactive protein and 8-isoprostane concentrations in diabetic mice compared to diabetic mice exposed to saline or non-diabetic mice exposed to DEP." (PMID 23587270, 2013). "Correlation studies revealed a high degree of positive association between tumor growth and each of CRP (r = 0.85) and leukocytosis (r = 0.89), thus attesting to a diagnostic/prognostic role for CRP." (PMID 19341447, 2009). "Nonspecific inflammatory parameters such as erythrocyte sedimentation, CRP, and leukocytosis-associating neutrophilia may reflect a systemic inflammatory burden for HS." (PMID 39229360, 2024). "It is evident that acute cholecystitis may not always present with the classic diagnostic criteria, including laboratory results (leukocytosis, elevated C-reactive protein) and physical exam findings (fever, RUQ pain, and + Murphy's sign)." (PMID 37525805, 2023). "(2021) on confirmed COVID-19 patients concluded that leukocytosis, neutrophilia, elevated neutrophil-to-lymphocyte ratio, activated partial thromboplastin time, D-dimer, lactate dehydrogenase, serum ferritin, and CRP are associated with the severity of the disease." (PMID 35755851, 2022). "The independent factors associated with early antibiotic therapy were leukocytosis (adjusted odds ratio (aOR), 3.95; 95% confidence interval (CI), 1.76–9.27), C-reactive protein ≥50 mg/L (aOR, 4.19; 95% CI, 1.84–10.21), and performing abdominal imaging studies (aOR, 3.44; 95% CI, 1.55–7.99)." (PMID 36670591, 2022). "The presence of potential risk factors of vomiting, leukocytosis, and CRP more significant than 40 mg/L may assist clinicians in ensuring an expedited surgical treatment." (PMID 35204926, 2022). "Similarly, they can have an associated leukocytosis, elevated c-reactive protein, and/or thrombocytosis." (PMID 36291833, 2022). "Moreover, intensive care was independently associated with leukocytosis and elevated C-reactive protein levels." (PMID 36118201, 2022). "Leukocytosis alone with elevated CRP levels was associated with ICU admission on the return visit." (PMID 32850531, 2020).
leukocytosis (continued). "Regarding the risk profile, patients positive for copeptin had higher hs-TnT concentrations measured at every time point; higher six-hour and maximal concentration of CK-MB; higher admission NT-proBNP, CRP, and leukocytosis and lower GFR; and higher GRACE risk score." (PMID 29619130, 2018). "In this study, more leukocytosis might be associated with disease severity (p = 0.001), but elevated CRP level was negatively correlated with the length of hospital stay." (PMID 30192893, 2018). "Indeed, our results confirm that biological tests (i.e. C-reactive protein and leukocytosis) have poor diagnostic value." (PMID 28945767, 2017). "Leukocytosis and positive CRP were associated with severe M.pneumoniae infection." (PMID 27836006, 2016). "Significant laboratory abnormalities include marked leukocytosis, thrombocytosis, and anemia in association with elevated acute phase reactants such as C-reactive protein (CRP), erythrocyte sedimentation rate (ESR), and serum ferritin which reflect an important systemic inflammatory response." (PMID 24303223, 2013). "We found that certain baseline characteristics of critically ill patients with 2009 influenza A (H1N1) may be associated with increased ICU admission, including elevated CRP, leukocytosis and more abnormalities in chest radiography." (PMID 20979619, 2010). "The authors of the study concluded that patients infected with CD strains that produce a high toxin titer have significantly elevated levels of inflammatory markers in the serum, including leukocytosis > 20 × 109 /L and CRP > 230 mg /L, which may be useful risk markers for mortality in CDI." (PMID 36422354, 2022). "Laboratory findings included leukocytosis, anemia, thrombocytosis, elevated C-reactive protein, and hypoalbuminemia." (PMID 41640915, 2026). "Examination revealed marked lower abdomen rebound tenderness and her laboratory tests showed leukocytosis and elevated C-reactive protein." (PMID 42226845, 2026). "Laboratory evaluation showed leukocytosis with a high absolute neutrophil count and mildly elevated C-reactive protein; blood culture grew Klebsiella pneumoniae, for which appropriate antibiotic therapy was initiated." (PMID 41660387, 2026). "Inflammatory marker levels were higher in LPP, including leukocytosis, neutrophilia, C-reactive protein, and procalcitonin (all p < 0.05)." (PMID 41684123, 2026). "Laboratory tests frequently reveal leukocytosis, elevated C-reactive protein (CRP), increased lactate levels, and creatinine." (PMID 41594310, 2026). "Laboratory studies revealed mild leukocytosis with neutrophilia and elevated C-reactive protein, while thyroid function tests were normal." (PMID 42253669, 2026). "Laboratory findings included leukocytosis (15.9 × 109/L) and elevated C-reactive protein (72.51 mg/L)." (PMID 42058417, 2026). "Laboratory evaluation revealed elevated inflammatory markers (ESR 55 mm/hr, CRP 20 mg/L), leukocytosis (16.58 × 109/L), markedly raised creatine kinase (19,937 IU/L), and troponin T levels." (PMID 42279552, 2026). "Laboratory results demonstrated leukocytosis (17,000/μL), normocytic anemia (hemoglobin 10.1 g/dL), thrombocytosis (672,000/μL), elevated inflammatory markers (CRP 145 mg/L, ESR 120 mm/h), and strongly positive perinuclear MPO-ANCA > 134 U/mL." (PMID 41515620, 2026). "Laboratory findings showed marked leukocytosis 19 000/mm3, an acute increase in C-reactive protein (CRP, 13.60 mg/dL), a hemoglobin of 11.8 g/dL, and a platelet count of 163 000/μL were discovered in blood tests, indicating severe inflammation." (PMID 41497096, 2026). "Laboratory tests showed leukocytosis (12 400/mm3), elevated C-reactive protein (46 mg/L), and creatinine 1.3 mg/dL." (PMID 42100609, 2026). "On admission, she presented with normochromic normocytic anaemia (7.7 g/dL), elevated inflammatory markers (CRP 250 mg/L), and leukocytosis (14,000/μL, neutrophils 10,000/μL)." (PMID 41627653, 2026).
leukocytosis (continued). "Laboratory tests revealed leukocytosis (13.3 × 10^9/L) and elevated C-reactive protein (45.4 mg/L) with normal procalcitonin (0.03 ng/mL)." (PMID 41938579, 2026). "Notable findings included leukocytosis (17,000/μL), normocytic anemia, thrombocytosis (672,000/μL), highly elevated inflammatory markers (CRP 145 mg/L, ESR 120 mm/h), and strongly positive MPO-ANCA (>134 U/mL)." (PMID 41515620, 2026). "Initial investigations showed leukocytosis, elevated C-reactive protein, and MRI findings of sulcal/cisternal widening and spinal cord signal changes." (PMID 41737236, 2026). "Blood analysis revealed elevated C-reactive protein levels and leukocytosis in 88.7% and 83.4% of the patients, respectively." (PMID 41597675, 2026). "Laboratory findings showed leukocytosis with neutrophilia, a markedly elevated creatine kinase and C-reactive protein." (PMID 42064248, 2026). "Significant leukocytosis (11.3 × 103/μL) and elevated C-reactive protein (252.8 mg/L) were found on laboratory investigations." (PMID 42022723, 2026). "Laboratory findings supported these observations: postmenopausal women demonstrated significantly elevated inflammatory markers, including higher median C-reactive protein levels and increased rates of leukocytosis." (PMID 41597675, 2026). "Laboratory evaluation revealed leukocytosis, elevated C-reactive protein, and increased procalcitonin." (PMID 41641255, 2026). "At admission, inflammatory markers were raised, with leukocytosis (15.6 ± 5.8 × 103/μL), neutrophilia (10.1 ± 4.7 × 103/μL), and elevated C-reactive protein (CRP) (median 43.2 mg/dL)." (PMID 42041326, 2026). "Exercise reduced leukocytosis by attenuating the low-grade inflammation, as evidenced by low levels of CRP." (PMID 41515269, 2026). "Traditional markers like leukocytosis and CRP maintain higher sensitivity for initial detection, while the addition of bilirubin enhances specificity, particularly for identifying complicated cases." (PMID 41185821, 2025). "Laboratory tests revealed leukocytosis (14,690 cells/μL, normal reference range [RR] 4-13.5 × 103 cells/μL) with neutrophilia (78.4%, RR 40–60%), and increased C-reactive protein ([CRP] 13.03 mg/dL, RR < 0.5 mg/dL)." (PMID 40682101, 2025). "The blood test results revealed elevations in procalcitonin to 15.02 ng/mL, leukocytosis count to 18.1 × 109/L, neutrophils to 97.1%, and C-reactive protein level of 51.50 mg/L." (PMID 40922240, 2025). "Laboratory evaluation revealed leukocytosis (21,190/μL), elevated C-reactive protein (11.4 mg/dL), and acute kidney injury, with serum creatinine increased to 3.81 mg/dL." (PMID 41010716, 2025). "Minor criteria include recurring fever, objective indications of aberrant bone remodeling with or without bone pain, a neutrophilic dermal infiltration on a skin biopsy, or leukocytosis and/or increased CRP." (PMID 39859314, 2025). "Laboratory tests revealed leukocytosis at 22,120/mm3 and an elevated C-reactive protein (CRP) level of 217 mg/L." (PMID 40364883, 2025). "Laboratory results showed leukocytosis of 9,910 cells/μL, platelets at 233,000 cells/μL, a prothrombin time (PT) ratio of 100%, D-dimer levels of 360 ng/mL, and a C-reactive protein (CRP) of 16.5 mg/L." (PMID 40165845, 2025). "CRP rises proportionally to IL-6-mediated hepatocyte stimulation and mirrors both systemic and local biliary inflammation more directly than leukocytosis or cholestatic indices." (PMID 40786322, 2025). "Laboratory studies revealed leukocytosis with a left shift, with elevated C-reactive protein (CRP) and elevated blood glucose level." (PMID 40671995, 2025). "Leukocytosis (14500 x 10^9/L), neutrophilia (85%), and raised CRP (13.11 mg/dl) and ESR (44 mm/hr) were observed." (PMID 40161166, 2025). "Laboratory findings showed leukocytosis (17.57 × 103/μL), elevated CRP (28.03 mg/dL), and a hemoglobin level of 14 g/dL." (PMID 40458360, 2025).